TBK1 (TANK binding kinase 1)
Diseases named in the same sentence as TBK1 in open-access papers (continued):
Sharing a sentence is not in itself a finding about the gene and the disease.
amyotrophic lateral sclerosis (62 papers, 2018 to 2026). Amyotrophic lateral sclerosis (ALS) is a neurodegenerative disease characterized by progressive muscular paralysis reflecting degeneration of motor neurons in the primary motor cortex, corticospinal tracts, brainstem and spinal cord. "Pathogenic mutations within the TBK1 gene leading to haploinsufficiency are causative of amyotrophic lateral sclerosis (ALS)." (PMID 40075110, 2025). "Dysregulation of TBK1-mediated p62 phosphorylation is linked to neurodegenerative diseases like Amyotrophic Lateral Sclerosis (ALS) and Frontotemporal Lobar Degeneration (FTLD)." (PMID 40643536, 2025). "Several studies have also demonstrated that TBK1 mutations are associated with the development of amyotrophic lateral sclerosis, an adult-onset neurodegenerative disorder affecting motor neurons." (PMID 38886689, 2024). "Mutations in the TBK1 gene have been identified in patients suffering from amyotrophic lateral sclerosis (ALS), including missense, frameshift, and truncating mutations." (PMID 37445986, 2023). "TBK1 has previously been associated with phenotypes related to respiratory distress and respiratory failure through its complex role in amyotrophic lateral sclerosis, matching the respiratory phenotypes associated with COVID-19 infections." (PMID 33682875, 2021). "OPTN and a key regulatory kinase, TBK1, both of which have been identified as genes linked to familial or sporadic amyotrophic lateral sclerosis, interact and are required for efficient mitophagy." (PMID 32556086, 2020). "We exome sequenced 699 familial amyotrophic lateral sclerosis patients and identified 16 TBK1 novel or extremely rare protein-changing variants." (PMID 30033073, 2018). "Mutations in TANK binding kinase 1 (TBK1) have been linked to amyotrophic lateral sclerosis." (PMID 30033073, 2018). "In amyotrophic lateral sclerosis (ALS), multiple ALS-related proteins, including TBK1, GRN, C9orf72 and TMEM106B, are implicated in endosomal sorting and endosomal lysosomal function." (PMID 38239560, 2023). "OPTN and TBK1 mutations have also been identified in patients with amyotrophic lateral sclerosis (ALS)." (PMID 36099048, 2022). "TANK-binding kinase 1 (TBK1) has been identified as a causative gene of amyotrophic lateral sclerosis (ALS) in the Caucasian population in 2015." (PMID 35283724, 2022). "Mutations of Ubiquilin 2 (UBQLN2) or TANK-binding kinase 1 (TBK1) are associated with amyotrophic lateral sclerosis and frontotemporal degeneration (ALS/FTD)." (PMID 32413959, 2020). "Limited copy number variations studies in amyotrophic lateral sclerosis: While CNVs in genes such as NEK1, TBK1, and C9orf72 have been linked to ALS, comprehensive, genome-wide CNV investigations are lacking." (PMID 40819305, 2026). "Amyotrophic lateral sclerosis (ALS) is characterised by the presence of genetic mutations in autophagy-related genes, including SQSTM1, OPTN, TBK1, VCP, and C9ORF72, which have been found to be linked to family variants of the illness." (PMID 37760929, 2023). "We also examine mechanisms for disruption of this process leading to neurodegeneration, focusing on the role of TBK1 in pathogenesis of Amyotrophic Lateral Sclerosis." (PMID 36226074, 2022). "Furthermore, mitophagy is impaired in Alzheimer disease, and loss-of-function mutations in the mitophagy regulator TBK1 (TANK-binding kinase 1) and the receptor protein, optineurin, are associated with ALS (Amyotrophic Lateral Sclerosis)." (PMID 34844982, 2022). "The importance of mitophagy in the pathogenesis of neurodegenerative diseases is supported by the identified mutations of proteins involved in mitophagy—primarily PINK1 and parkin in Parkinson’s disease, optineurin and TBK1 in amyotrophic lateral sclerosis, and p62/SQSTM1 in frontotemporal dementia." (PMID 34638589, 2021).
amyotrophic lateral sclerosis (continued). "Mutations in the autophagy receptors p62 and OPTN1 cause selective autophagy defects in amyotrophic lateral sclerosis (ALS); TBK1 is a kinase responsible for the phosphorylation of OPTN1, and its mutations are associated with ALS and frontotemporal dementia." (PMID 34073798, 2021). "Here, we present the PTMs and PTVs of four major amyotrophic lateral sclerosis (ALS) proteins, SOD1, TDP-43, FUS, and TBK1." (PMID 39201350, 2024). "The TANK-binding kinase 1 gene (TBK1) is on the list of genes that can contribute to the development of FTD as well as the related neurodegenerative disease amyotrophic lateral sclerosis (ALS)." (PMID 34800171, 2022). "TANK binding kinase 1 (TBK1) is serine/threonine protein kinase member of the inhibitor of nuclear factor-kB kinase family, with links to the etiology of familial as well as idiopathic Amyotrophic Lateral Sclerosis." (PMID 41191168, 2025).
Obesity (46 papers, 2013 to 2026). Accumulation of substantial excess body fat. "This suggests that obesity-associated Fabp1 upregulation is promoted by fatty acids via the PPARα and TBK1–IKKε–IRF3 pathways." (PMID 36400935, 2022). "To investigate the underlying mechanism by which BJ treatment inhibits obesity and improves metabolism, we analyzed the activity and expression levels of IKKε and TBK1 in adipose tissue." (PMID 35962183, 2022). "This work not only elucidates the poorly defined upstream activation of mTORC2 but also improves our understanding of the contribution of TBK1 and mTORCs to physiology and pathologic conditions such as tumorigenesis and obesity-linked metabolic disorders." (PMID 34245780, 2021). "Beyond its well-known role in innate immunity, TBK1 has been implicated in oncogenesis and metabolic disorders linked to obesity such as type II diabetes, similar to mTOR and Akt." (PMID 34245780, 2021). "The deficiency of TBK1 in adipocytes leads to the attenuation of high fat diet-induced obesity, but the exaggeration of adipose tissue inflammation, indicating a loss of the positive correlation between adiposity and adipose tissue inflammation." (PMID 33193441, 2020). "Taken together, these results indicate that the enhanced liver TBK1 phosphorylation is positively correlated with obesity-associated glucose dysregulation and insulin resistance." (PMID 28743914, 2017). "We previously identified IKK-ε and TBK1 as promising therapeutic targets for the treatment of obesity and associated insulin resistance." (PMID 25581158, 2015). "Adipocyte‐specific TBK1 deficiency attenuates HFD‐induced obesity by increasing energy expenditure." (PMID 39158380, 2025). "In addition, they establish the TBK1-mTORC2 pathway as a potential target for therapeutic intervention to treat cancer and obesity-linked metabolic disorders." (PMID 34245780, 2021). "Moreover, the loss of TBK1 in adipocytes attenuates HFD-induced obesity via increasing mitochondrial biogenesis and energy expenditure." (PMID 33193441, 2020). "Inhibiting TBK1 with amlexanox improves obesity, insulin sensitivity, and glucose tolerance in HFD‐fed mice, ob/ob mice, and T2D patients." (PMID 39158380, 2025). "Supporting this, adipose-specific knockout of TBK1 reduced HFD-induced obesity by increasing energy expenditure, likely due to enhanced AMPK activity, which promotes catabolic processes." (PMID 39669992, 2024). "It was reported that the abnormal expression of TBK1 is related to obesity, diabetes, even and NAFLD." (PMID 38436022, 2024). "Recent studies have demonstrated that amlexanox, a selective inhibitor of IkB kinase epsilon (IKKε) and TANK-binding kinase 1 (TBK1), suppresses a range of diseases or inflammatory conditions, such as obesity-related metabolic dysfunction and type 2 diabetes." (PMID 38302598, 2024). "Here were found many genes whose expression positively correlates with obesity, insulin resistance, type-2 diabetes and chronic inflammation, such as Irs2, Angptl4, Lepr, Camkk2 and Tbk1." (PMID 37957359, 2023). "It has been shown in mice adipose tissue that TBK1 inhibits AMPK activity causing suppression of energy expenditure, obesity, and inflammation." (PMID 36828933, 2023). "Conversely, TBK1 inhibition has been found to increase energy expenditure, reduce obesity and insulin resistance in mice." (PMID 36828933, 2023). "Previous studies show that the stimulator of interferon genes (STING) signaling plays crucial roles in obesity-induced chronic inflammation via TANK-binding kinase 1 (TBK1) pathways." (PMID 36782056, 2023). "To further investigate the mechanism by which BJ inhibits obesity, we overexpressed or knocked down TBK1 and IKKε in 3T3-L1 adipocytes in vitro." (PMID 35962183, 2022). "The role of TBK1 in the pathogenesis of inflammatory diseases, T2D, obesity, and neurodegenerative diseases has been discussed in several outstanding reports." (PMID 35395857, 2022).
Obesity (continued). "Together, our findings support that co-crystal BJ is likely to be an effective agent for treating obesity and its related metabolic diseases targeting TBK1 and IKKε." (PMID 35962183, 2022). "Our previous study showed that activated TBK1 induces obesity-induced ubiquitinated protein inclusions in liver tissue and that inhibiting the TBK1 pathway protects against fibrotic liver pathologies in mouse models of obesity and nonalcoholic steatohepatitis." (PMID 34858401, 2021). "For example, TBK1 expression and activity are induced in adipose tissue in obesity by elevated expression of proinflammatory cytokines such as tumor necrosis factor α." (PMID 34563542, 2021). "Although it was reported that TBK1 expression and activity are induced in adipose tissues during obesity and insulin resistance, the role of TBK1 in the pathogenesis of metabolic disease was unclear." (PMID 33193441, 2020). "The inflammation-induced TBK1 activity produced during obesity represses energy expenditure and promotes anabolism, which further enhances obesity through a feedforward loop." (PMID 33193441, 2020). "Amlexanox is an FDA‐approved drug for the treatment of aphthous ulcers, rediscovered as IKKε/TBK1 inhibitor, that in mice improves obesity‐related metabolic dysfunction, suggesting that it targets processes linking inflammation to metabolism." (PMID 31930708, 2020). "In this review, we summarize current data on the functions and molecular mechanisms of TBK1 and IKKε in orchestrating inflammation to cancer, obesity, and diabetes." (PMID 30791439, 2019). "Adipocyte-specific TBK1 knockout (ATKO) attenuated HFD-induced obesity by increasing energy expenditure." (PMID 30791439, 2019). "Recent evidence suggests that tumor necrosis factor α (TNFα) induces TBK1 and IKKε, which play pivotal roles as mediators of obesity-induced systemic low-grade inflammation." (PMID 30791439, 2019). "We contemplate that in later years, the molecular routes, together with TBK1/IKKɛ-NF-κB, which contribute to the regulation of the activation of NF-κB during obesity, will be deciphered." (PMID 28319103, 2017). "Taken together, these data suggest that similar to what is observed in obesity, overexpression of IKKε or TBK1 can repress lipolytic signaling." (PMID 24368730, 2013). "Both TBK1 and IKKε are induced in response to obesity-dependent inflammation, and appear to phosphorylate PDE3B on the same residues with equal efficiency." (PMID 24368730, 2013). "Obesity-dependent activation of the NFκB pathway increases the levels of a pair of enzymes, IKKε and TBK1." (PMID 24368730, 2013). "Notably, TBK1 can suppress inflammation by attenuating NF-κB and depends on prior adipose inflammation for its activation in obesity." (PMID 41148235, 2025). "Notably, TBK1 exhibits dual regulatory functions, attenuating energy expenditure in obesity while exerting anti‐inflammatory effects via NF‐κB degradation." (PMID 41250907, 2025). "Mitochondrial and oxidized DNA activate cGAS‐STING in adipocytes and macrophages, exacerbating inflammation and reducing thermogenesis, while the downstream kinase TBK1 plays a dual role by inhibiting energy expenditure during obesity and suppressing inflammation during nutrient deprivation." (PMID 39158380, 2025). "In obesity, the activation of TBK1 will inhibit NF-κB-inducing kinase (NIK), thus inhibiting NF-κB from achieving the effect of reducing inflammation, showing that TBK1 plays a bidirectional role in energy storage and metabolism to achieve a balance between energy metabolism and inflammation." (PMID 38312740, 2024). "Aberrant TBK1 activity can also contribute to diabetes and obesity." (PMID 39103493, 2024). "Placing TBK1 in this nutrient-dependent pathway for mTORC1 activation may be of relevance for the anabolic effects of TBK1 in the context of diabetes and obesity." (PMID 39103493, 2024).
Obesity (continued). "To understand obesity-related target genes, we used PubMed Abstracts, GeneCards, OMIM, and DisGeNET databases for network analysis, and identified 9481 common obesity-related genes, among which 1791 were screened out due to high relevance scores, such as Tbk1 and Ikbke." (PMID 35962183, 2022). "Therefore, inhibiting IKKε and TBK1 can ameliorate obesity, and its inflammation, and alleviate obesity-related metabolic disorders." (PMID 35962183, 2022). "The mechanism by which BJ reduces obesity may be partly due to its inhibitory effects on the expression of TBK1 and IKKε, and may occur through two different pathways: the TBK1/AMPK/UCP1 pathway and the IKKε/adrenergic/cAMP pathway." (PMID 35962183, 2022). "Obesity-induced chronic inflammation increases the production of proinflammatory cytokines, such as TNFα, in adipose tissue, and these cytokines stimulate NF-κB activity in adipocytes and induce TBK1 and IKKε expression." (PMID 35962183, 2022). "In addition, increased activities of IKKε and TBK1 can lead to obesity-mediated catecholamine resistance, primarily in adipocytes, by mediating PDE3B phosphorylation to restrict cAMP levels." (PMID 34848839, 2021). "Consistent with a negative role of adipose cGAS‒STING signaling in regulating thermogenesis, adipose-specific knockout of TBK1 attenuates HFD-induced obesity by increasing energy expenditure, which has been attributed to increased AMPK activity that enhances catabolism." (PMID 34665236, 2021). "The expression and activity of TBK1 are induced in adipose tissues during diet-induced obesity, suggesting a potential involvement of this kinase in obesity-induced metabolic dysfunction." (PMID 34665236, 2021). "Furthermore, amlexanox, an FDA‐approved drug targeting IKKε and its homologue TBK1, delayed in vivo tumour formation in a combined genetic mouse model of breast cancer and high‐fat diet‐induced obesity/inflammation." (PMID 31930708, 2020). "Finally, we show that amlexanox, an FDA‐approved drug targeting IKKε and its homologue TBK1, delays tumour appearance in vivo in a combined genetic mouse model of breast cancer and diet‐induced obesity." (PMID 31930708, 2020). "Thus, adipose-specific deletion of TBK1 (ATKO) attenuates diet-induced obesity with exacerbation in glucose intolerance and insulin resistance, whereas genetic deletion of IKKε increases energy expenditure with improvement in insulin sensitivity on a HFD34,35." (PMID 33168920, 2020). "Consistent with previous finding showing increased activity of TBK1 and IKKε in the livers of mice with obesity, we also found significantly increased phosphorylation levels of TBK1 and IKKε in the livers of mice fed with DDC diet compared with those of mice fed with chow diet." (PMID 31821710, 2020). "Furthermore, TBK1 is involved in the inflammatory response in obesity and hypertension and contributes to phosphorylation of the insulin receptor thus impairing its function and supporting insulin resistance." (PMID 25997745, 2015). "TBK1 plays a key role in linking inflammation to insulin resistance in obesity." (PMID 25768116, 2015). "Additionally, inhibition of key inflammatory kinases, including IκB kinase ε (IKKε) and TANK-binding kinase 1 (TBK1), using compounds such as amlexanox, has been shown to restore catecholamine sensitivity and reverse metabolic dysfunctions associated with obesity." (PMID 41226484, 2025). "Recent studies have demonstrated that TBK1 links the pathogen-stimulated processes of inflammation/immunity, metabolism, and proliferation involved in many human diseases, including inflammatory diseases, type II diabetes (T2D), obesity, neurodegenerative diseases, and some cancers." (PMID 35395857, 2022).